IRS1 (insulin receptor substrate 1)
Diseases named in the same sentence as IRS1 in open-access papers (continued):
Sharing a sentence is not in itself a finding about the gene and the disease.
cancer (continued). "In this study, we established mouse NIH/3T3 cells that overexpressed IRS-1, so mimicking cancers with increased IRS-1 expression levels; we found that the IRS-1 overexpressing cells grow more rapidly than control cells do." (PMID 22788551, 2012). "Involvement of theIGF-1/AKT pathway in cancer cachexia was confirmed by our data showing decreased AKT activation as evidenced bydown-regulated IGF-1, IRS-1 and IGFBP5." (PMID 21069263, 2011). "Many of the motifs are conserved between the two family members, and IRS-1 and IRS-2 have been reported to activate common signaling pathways including PI3K and the Erk1/2 MAPK kinases in a variety of cancer model systems." (PMID 19534786, 2009). "This is likely due to the release of the S6-dependent negative feedback loop on IRS-1, a common survival mechanism in cancer cells during nutrient stress." (PMID 41514527, 2025). "Theoretically, IRS1 and IRS3 would be identical when the patients’ cancers diminished." (PMID 40643471, 2025). "It has been shown that the A isoform of the insulin receptor (IR-A) is often overexpressed, and its stimulation induces changes in the expression of the insulin receptor substrates (IRS-1 and IRS-2), which are expressed differently in the different types of cancer." (PMID 36975518, 2023). "Experimental studies have shown that OP and NMBR inhibitor BIM-23127 inhibits independent autophosphorylation of IRβ and IRS-1 in HTC-IR cells, blocking Neu-1-mediated transactivation of the IR, which may be used as a therapeutic target for cancer." (PMID 36831374, 2023). "This releases TNS2 from its binding partner IRS-1, which in turn upregulates Glut4 and PDK1, enzymes that may play a critical role in the glucose metabolism of cancer cells." (PMID 35804982, 2022). "Interestingly, PIK3/AKT signaling cascade is specifically targeted by the onco-suppressor miR-126, as it is well documented that IRS-1 and PIK3R2, two upstream components of this pathway, are directly inhibited by miR-126 in several cancer types, including BC." (PMID 35628294, 2022). "Notably, the activation of the PI3K/AKT/mTOR pathway occurs in many types of cancer, and is one of the key downstream transduction signaling pathways of the IGF1R/IRS1 interaction." (PMID 33723215, 2021). "Besides, upon endocytosis, NE is to bind insulin receptor substrate-1 (IRS-1), which removes the inhibitory effect of IRS-1 on phosphatidylinositol 3-kinase (PI3K) to enhance the proliferation of cancer cells." (PMID 32849640, 2020). "Ingeneral, IRS1 suppresses, while IRS2 induces the migration of cancer cells." (PMID 30807634, 2019). "Furthermore, AMPK inhibits IRS1 mediated IR and IGFR oncogenic signaling via PI3K/Akt/mTOR, which, potentially, also contributes to the anti-cancer effect of metformin." (PMID 31835318, 2019). "We hypothesized that mTORC1 inhibition activates the IGF-1R/InsR/IRS-1/2 axis in an ER-dependent manner to drive PI3K/AKT and promote cancer cell survival, implicating ER in survival signaling induced by mTORC1 inhibition." (PMID 29507656, 2018). "Referring to the literature, we hypothesize that IRS‐1 exerts an allocative function between the survival and the proliferation pathway in connection with SRC in the examined self‐sustaining cancer cells." (PMID 28675785, 2017). "Similarly, ectopic miR-126 has been proposed to downregulate IRS1, reduce AKT signaling and inhibit cytosolic sequestration of FOXO1 in response to mitochondria-destabilizing stimuli involved in cancer induction and progression." (PMID 27999212, 2017). "Since IRS-1 is required for IGF-1R stimulation of cell proliferation and IRS-2 is involved in cancer motility and metastasis, inhibition of their function or expression could be therapeutically exploited." (PMID 29152592, 2017). "Moreover, TMEPAI is able to downregulate insulin receptor substrate-1 (IRS-1), an EMT suppressor which plays an important role in maintaining the epithelial phenotype in cancer cells, via ROS." (PMID 26078812, 2015).
cancer (continued). "Therefore, it is conceivable that N-NOSE may have detected a small number of residual cancer cells remaining only within the duct following NAC and prior to surgery, thereby contributing to the observed differences in IRS1 and IRS3." (PMID 40643471, 2025). "The role of IRS1 in cancer in relation to tau has not been examined in the same way." (PMID 39469929, 2024). "In addition, IRS1 is related to cell proliferation in cancer, and we did not observe the phosphorylation of IRS1 in this study." (PMID 36975518, 2023). "In non-cancer tissues like adipocytes, RAGE is involved in inflammation-dependent Ins resistance, a condition characterized by a reduced ability of Ins to activate IR/IRS1/AKT signaling; in these contexts, the inhibition or ablation of RAGE restores Ins sensitivity and glucose homeostasis." (PMID 37461077, 2023). "It is not clear whether cancer cells could hijack this mechanism to regulate IRS-1 function in order to gain growth advantage." (PMID 33991522, 2021). "In addition, insulin mediates insulin receptors, up-regulates MMP-2 expression, stimulates insulin receptor substrate-1 (IRS-1), and then activates the PI3K/AKT and MAPK signaling pathways to promote cancer cell proliferation and enhance cancer cell migration ability." (PMID 34485124, 2021). "Thus, cancer cells adapt very rapidly to PI3K inhibition, mainly due to feedback signals leading to activation or enhanced expression of growth factor receptors, such as IR/IRS1/IGF-1R, which, in turn, reactivate PI3K." (PMID 34638901, 2021). "Externally liberated NE has been shown to have a profound effect on neighboring tissues in cancer cells, where its uptake led to the degradation of IRS1, thereby uncoupling the PI3K pathway from the negative regulatory effect of IRS1, thereby leading to uncontrolled growth." (PMID 28659928, 2017). "Consistently, deletion of miR-148a or miR-152 binding regions in 3′UTR of IRS-1 did not exert the effect of miR-148a or miR-152 overexpression on inhibition of cell proliferation, indicating that these miRNAs affect cancer cell proliferation via IRS-1 suppression." (PMID 25628647, 2014). "In some cancer cells rapamycin actually promotes oncogenic activity, due to an activation of AKT and other signalling molecules of the IGF-1R/IRS-1 signalling system which reflects the loss of a negative feedback regulation on IRS-1 and TORC2." (PMID 24970820, 2014). "Given the differences between IRS1/2 and IRS4 at the molecular level, knowledge of the signaling pathways controlled by IRS4 may enable the design of new drugs for the treatment of cancer without causing deleterious effects on the regulation of insulin and/or IGF1 signaling cascades." (PMID 37760618, 2023). "In the absence of TNS2, elevated IRS1 signaling may promote tumorigenicity in cancer cells." (PMID 27203214, 2016). "However, IRS1 and IRS2 may have divergent functions in cancer metastasis." (PMID 23112878, 2012). "Furthermore, activated IGF1R has been recently shown to translocate to the nucleus in both non-malignant tissues and cancers, although it remains to be determined whether IRS1 and IGF1R interact in this subcellular location." (PMID 22558377, 2012). "In this study we show that while expression of IRS4 is generally low in the studied panel of cancer cell lines, it is high in NCI-H720, DMS114, HEK293T and HEK293AAV cells and that PI3K signalling in these cell lines relies on IRS4, but not IRS1." (PMID 24039912, 2013). "In most cancer cell types, rapalogs such as RAD-001, increased Akt phosphorylation through inhibition of a negative feed-back loop based on mTORC1/p70S6K/IRS1/PI3K." (PMID 22885370, 2012). "However, the roles of adaptor proteins IRS1 and IRS2 have not been investigated in this type of cancer." (PMID 36975518, 2023).
cancer (continued). "The low-level activation induced by ganitumab in the Balb/C 3T3 hIGF1R and 32D hIGF1R/IRS-1 cells appeared to be specific to cells that overexpress IGF1R, since it could not be reproduced in other human cancer cell lines." (PMID 23383308, 2013). "By further examining changes in the PI3K/AKT/mTOR pathway looking at the downstream transcription factors S6K and eIF4E, and PRAS40 (inhibits mTOR and IRS-1), we could identify their role in the negative feedback of the PI3K pathway, an effect commonly seen in various cancers and cancer models." (PMID 37908840, 2023). "However, in specific cancer types, such as multiple myeloma and T-cell acute lymphoblastic leukemia, DEPTOR exhibits oncogenic properties by activating AKT to alleviate the negative feedback effect of the mTORC1 substrate, S6K1, on IRS1/PI3K signaling." (PMID 33184290, 2020). "We and others have shown that inhibition of mTORC1 relieves negative feedback on upstream activators, including IRS-1, IGF-1R, human epidermal growth factor receptor 3 (HER3), and PI3K, which may subsequently promote cell survival and antagonize the anti-cancer effects of mTORC1 inhibitors." (PMID 29507656, 2018). "In oncology, IRS1 and IRS2 knockout mice as well as IRS1- and IRS2-overexpressing murine models were used to elucidate the function of these proteins in solid tumors, providing evidence of distinct and nonredundant functions for both proteins in cancer development and progression 106, -108." (PMID 30328953, 2018).
metabolic disorders (34 papers, 2011 to 2025). "Here, we found that the metabolic disease-associated G972R mutation undermined the ability of IRS-1 to undergo phase separation in vitro and in cells." (PMID 35764611, 2022). "They reported that overexpression of MG53 caused metabolic disorders in mice through down regulation of IRS-1, an E3 ubiquitin substrate of MG5321." (PMID 31604915, 2019). "Polymorphisms in or near the IRS1 gene are often associated with metabolic diseases in humans." (PMID 35764611, 2022). "EA can regulate peripheral metabolic disorders, significantly increase IRS-1 levels, promote AKT phosphorylation, and enhance insulin sensitivity." (PMID 38283741, 2023). "Our findings delineate a mechanism in which LLPS of IRS-1-mediated signalosomes serves as an organizing center for insulin/IGF-1 signaling and implicate the role of aberrant IRS-1 LLPS in metabolic diseases." (PMID 35764611, 2022). "JNK is one of the major inflammatory cytokines to inhibit insulin signaling via the induction of IRS1 phosphorylation at serine residues in hypertensive and metabolic diseases." (PMID 32851077, 2020). "In turn, the activation of p70S6K by mTORC1 promotes the phosphorylation of IRS1 and reduces its stability, an auto-regulatory pathway or negative feedback loop that has been shown to have profound implications for both metabolic diseases and tumorigenesis." (PMID 26536660, 2015). "We selected the molecules insulin receptor (IR) and insulin receptor substrate-1 (IRS-1) for their potential role in metabolic disorders affecting mental function." (PMID 22163304, 2011). "Importantly, metabolic disease-derived G972R mutation results in a reduced ability of LLPS, potentially implicating the involvement of aberrant IRS-1 phase separation in various metabolic disorders." (PMID 35764611, 2022). "All these findings suggest that aberrant LLPS of IRS-1 is involved in metabolic diseases." (PMID 35764611, 2022). "Unregulated inhibition may involve a constitutive activation of S6K1 that could inhibit IRS1 signaling and promote its degradation resulting in IR and the development of metabolic diseases." (PMID 36224569, 2022). "The metabolic disease-associated G972R mutation impaired the self-association and LLPS of IRS-1." (PMID 35764611, 2022). "IRS1 has been considered a candidate gene for human metabolic disorders, especially in T2DM." (PMID 32411229, 2020). "In metabolic disorders, such as NAFLD and T2DM, impaired IRs-1 level was observed, for instance, lipid accumulation in the liver was closely associated with increased serine phosphorylation of IRs-1." (PMID 31803542, 2019). "Insulin receptor substrate 1 (IRS1) is a protein phosphorylated by insulin receptor tyrosine kinase, which acts as an essential regulator in the progression of metabolic diseases." (PMID 36699468, 2022). "The data suggest that aging subjects develop cardiac abnormalities due to metabolic disorders in numerous metabolites as well as alterations in gene expressions, such as SOS1, CREB, IRS1, GRB2 and GSK3β." (PMID 30669571, 2019). "In this study, we found a significant negative correlation between peripheral glucose, lipid, HOMA-IR, IRS-1, and p-AKT levels, indicating that peripheral metabolic disorders may influence the sensitivity of the central insulin pathway." (PMID 38283741, 2023). "In the context of metabolic disorders, studies suggest that melatonin restores the activity of the PI3K/AKT/mechanistic target of rapamycin (mTOR) pathway, reduces insulin receptor substrate-1 (IRS-1) phosphorylation, and increases insulin-like growth factor 1 (IGF-1) activity." (PMID 40722923, 2025).
infection (22 papers, 2009 to 2025). The state of being infected such as from the introduction of a foreign agent such as serum, vaccine, antigenic substance or organism. "For human viruses, two proteins encoded by Human cytomegalovirus (HCMV), TRS1 and IRS1, which are characterized by inhibiting autophagy during infection." (PMID 39014281, 2024). "At 24 hours post-infection, C002 (Δγ134.5, IRS1, mIL-12) produced significantly greater infectious virus than did M002 (1.19x107 PFU/ml vs. 1.5x106 PFU/ml, p=0.008) or the control Δγ134.5 oHSV (1.19x107 PFU/ml vs. 4.9x105 PFU/ml, p=0.0064)." (PMID 38895115, 2024). "In agreement with the reduced protein abundance of AKT1 after MPXV infection, AKT1-regulated sites were less phosphorylated over the course of the infection, e.g., IRS1 pS629, PDCD4 pS457." (PMID 39117661, 2024). "Three days after infection, IRS-1 expression and insulin sensitivity were tested under both basal and IR states." (PMID 31723029, 2019). "HCMV encodes two immediate-early gene products that specifically target PKR as a means of downregulating the IFN response and maintaining high levels of viral gene transcription during infection: IRS1 and TRS1." (PMID 30134546, 2018). "TNF-α inhibits IRS-1, GLUT4 and adiponectin in TNF-α-treated control cells, however, infection with Ad:IGFBP-3 restored IRS-1, GLUT4 and adiponectin mRNA and protein levels." (PMID 23383064, 2013). "Interestingly, the high dose OA+EO treated group showed a similar profile to the infection group, with a limited number of phosphorylation changes but among those pro-inflammatory and proliferative (for example NFkB, mTOR, IRS1, HSP90)." (PMID 38835764, 2024). "The upregulation of PTPs after infection may increase the dephosphorylation of IRS-1 and further reduce the effect of insulin signaling." (PMID 38441470, 2024). "Likewise, mRNAs for two other IE genes, UL69 and IRS1, showed reduced accumulation during infection of cells expressing enzymatically competent myr-Akt relative to that of the K179M mutant control setting." (PMID 35946797, 2022). "Infection with Ad-IRS1 significantly decreased high glucose-induced podocyte apoptosis by 54 ± 21%." (PMID 32238837, 2020). "IRS1 protein was reduced after 48 hours of infection in the presence of metformin." (PMID 23133528, 2012). "Our data revealed that infection transiently elevated PI3K and AKT at early stages (12–24 h), followed by a marked reduction at later time points, along with decreased IRS1, IRS2, and GLUT1 expression." (PMID 41294830, 2025). "In summary, we monitored the expression patterns of five candidate genes (GF, RTK, IRS1, PP2A and PTEN) during the infection process and explored the role of the PI3K/AKT pathway." (PMID 35205292, 2022). "Work using an IRS1 and TRS1 double mutant (ΔIRS1/ΔTRS1) to investigate PKR modulation during infection was instrumental in uncovering another HCMV gene product that alters the host cell’s ability to sense viral dsRNA: ORF94 (UL126a)." (PMID 30134546, 2018). "Moreover, the upregulation of IRS1 and MEF2c mRNAs in SARS-CoV-ΔE versus WT infection correlated with miRNA-145a and 223 downregulation, respectively." (PMID 35229638, 2022). "Only 3 (IRS1, MEF2c, and GZMB) out of 29 miRNA predicted mRNA targets showed statistically significant expression changes (FC > 2; FDR < 0.05) in SARS-CoV-WT versus ΔE infection." (PMID 35229638, 2022). "Therefore, phosphorylation of IRS-1 at Ser307 was further examined in our study, and we observed a similar increase of pIRS-1 at Ser307 with HCV 2a infection and core protein transfection." (PMID 25645159, 2015). "On infection with Ad:EV, Ad:IGFBP-3 and Ad:IGFBP-3GGG mutant, semi-quantitative PCR shows that the effect of Ad:IGFBP-3GGG on the mRNA levels of GLUT4, IRS-1, adiponectin and MCP-1 was similar to Ad:IGFBP-3 suggesting that IGFBP-3 effect on the NF-κB pathway in adipocytes was IGF-independent." (PMID 23383064, 2013).
infection (continued). "Similarly in the LCMV-infected primate, IRS1 expression is decreased and expression of IRS2 is moderate, but SOCS2 is up-regulated (7.2-fold) at the pre-viremic stage of infection." (PMID 19216742, 2009). "Similarly, IRS1 and IRS2 showed sustained downregulation throughout 12–72 h post-infection." (PMID 41294830, 2025).
neurodegenerative disease (7 papers, 2017 to 2025). A disorder of the central nervous system characterized by gradual and progressive loss of neural tissue and neurologic function. "Dysregulation of brain IRS-1 contributes to developing brain insulin resistance (BIR), a hallmark of AD and other neurodegenerative diseases." (PMID 40498212, 2025). "The GLP-1 agonist exenatide, has been shown to alleviate brain IR in AD by modifying the pattern of IRS-1 phosphorylation and be neuroprotective against a variety of neurodegenerative diseases and stroke." (PMID 28515688, 2017). "However, other mechanisms of impaired insulin signaling cascade such as IRS1 and GSK-3 phosphorylation in the pathogenesis of AD as well as other cellular processes need further investigation for development of more effective therapeutic strategy for this devastating neurodegenerative disease." (PMID 31143098, 2019).
adenocarcinoma (4 papers, 2012 to 2023). A common cancer characterized by the presence of malignant glandular cells. "In this study, IRS-1 was relatively highly expressed in A549, H1299, and LTEP-a2 cells, which might be due to these NSCLC cells being adenocarcinoma cells." (PMID 34443299, 2021).
inflammation (2 papers, 2015 to 2025). Aberrant reaction of the microcirculation characterized by movement of fluid and leukocytes from the blood into extravascular tissues. "Chronic inflammation is one of the risk factors for abnormal IRS-1 serine 307 phosphorylation." (PMID 41154464, 2025). "IL18rap, MMP10 and Irs1 have been recently shown to play a role in the pathogenesis of CNS inflammation." (PMID 25993608, 2015).
IRS1 also shares sentences with these, for which no sentence is quoted: hyperlipidemia (8 papers); cardiovascular disease (5); diabetic retinopathy (4); lipid metabolism disorders (4); Hypoinsulinemia (3); Abdominal obesity (2); adrenal cortical carcinomas (2); amyloid (2); brain disorder (2); Cirrhosis (2); cognition disorder (2); fibrosarcoma (2); liposarcoma (2); myeloproliferative neoplasm (2); myocardial ischemia (2); progressive supranuclear palsy (2); renal cell carcinoma (2); retinopathy (2); rhabdomyosarcoma (2); uveal melanoma (2); anaphylaxis (1); ankylosing spondylitis (1); autism spectrum disorder (1); B cell lymphoma (1); bacterial infections (1); campomelic dysplasia (1); cerebrovascular disease (1); chronic hepatitis (1); chronic kidney disease (1); chronic pancreatitis (1).
A further 61 diseases each share a sentence with IRS1 in 1 paper.